MYCN (MYCN proto-oncogene, bHLH transcription factor)
Diseases named in the same sentence as MYCN in open-access papers (continued):
Sharing a sentence is not in itself a finding about the gene and the disease.
neuroblastoma (continued). "MYCN-amplified neuroblastoma is a high-risk disease with very few treatment options and poor outcome." (PMID 29954071, 2018). "In another study conducted on a wide range of neuroblastoma cell lines, overexpression of the c-kit gene was most often associated with the amplification of the MYCN gene." (PMID 30116755, 2018). "As also demonstrated in MYCN-amplified neuroblastomas, the susceptible SCLCs died via BIM- mediated apoptosis following disruption of BIM:BCL-2 complexes." (PMID 30234143, 2018). "Neuroblastoma (NB) is the most common pediatric malignancy diagnosed before the first birthday in which MYCN oncogene amplification is associated with poor prognosis." (PMID 30344930, 2018). "In particular, SMC2 has been shown to be dysregulated or mutated in pyothorax-associated lymphoma (PAL), MYCN-amplified neuroblastoma, gastric and colorectal cancers." (PMID 29467813, 2018). "Chromosomal amplification of the MYCN locus occurs in 25% of all neuroblastomas and is associated with poor prognosis." (PMID 30621745, 2018). "MYCN amplification or 11q loss of heterozygosity is found in many high-risk neuroblastomas and correlates with poor prognosis and treatment relapse." (PMID 28924803, 2018). "A further mechanism causing MYCN aberrant activation can be mediated by the hot spot mutation c.131C>T (p.Pro44Leu) initially identified in neuroblastoma as an acquired somatic event with predicted gain of function." (PMID 30344923, 2018). "A small number of genetic mutations have been identified in neuroblastoma tumours, the first and best characterised is amplification of a variable sized amplicon containing the MYCN gene." (PMID 29301505, 2018). "Aurora A overexpression in neuroblastoma is associated with advanced clinical states, MYCN amplification, disease relapse, and progression." (PMID 29678897, 2018). "We did not observe any copy number alterations of these two chromosomes in the murine tumors but did find a Tp73 mutation in one of the MYCN driven tumors, this gene is located at the human 1p36 region that is frequently deleted in high-risk neuroblastoma." (PMID 29492199, 2018). "There are studies which demonstrated that overexpression of miR-92, miR-106a, miR-17-5p, and miR-93 in neuroblastoma were functionally linked to MYCN amplification." (PMID 29547527, 2018). "The association between activating ALK mutations and MYC or MYCN is observed in other malignancies including neuroblastoma and anaplastic large cell lymphoma (ALCL)." (PMID 29507657, 2018). "miR-542-5p was first reported dysregulated in neuroblastoma and its expression levels were very significantly inversely correlated with the amplification of MYCN, a well-known oncogene that is associated with a variety of tumors." (PMID 30467286, 2018). "MYCN is deregulated through genomic amplification in ~40% of high-risk neuroblastomas, while MYC is frequently deregulated in a high proportion of the remainder." (PMID 29799508, 2018). "We sought to determine a functional role for MYCNOS-01 in alveolar rhabdomyosarcoma and neuroblastoma cells and identify any associated regulatory effects between MYCN and MYCNOS-01." (PMID 29466962, 2018). "NBT treatment decreased the expression of a neuroblastoma-derived MYC (MYCN) and multidrug resistance-associated protein 1 (MRP1) as well as downregulating Akt, GSK3β, and β-catenin." (PMID 30486290, 2018). "Neuroblastoma exhibits intra- and intertumoural heterogeneity, with high risk tumours characterised by poor differentiation, which can be attributable to MYCN-mediated repression of genes involved in neuronal differentiation." (PMID 29505958, 2018).
neuroblastoma (continued). "MYCN, which is amplified in approximately one-third of neuroblastomas and associated with high-risk behavior, is a transcription factor that regulates gene expression of ODC." (PMID 30262852, 2018). "Author’s response: High-risk neuroblastoma are clinically defined as patients with stage 4 and age older than 18 months at diagnosis or patients of any age and stage with MYCN-amplified tumors." (PMID 30012197, 2018). "Mutations previously reported in human neuroblastoma were enriched in the MYCN driven mouse tumors (p-value of 0.0278, Fisher’s exact test)." (PMID 29492199, 2018). "The identified association between high risk MYC and MYCN driven tumors and elevated lipids in medulloblastoma and neuroblastoma is also notable." (PMID 29541417, 2018). "Specifically, the amplification of the MYCN oncogene is associated with poor prognosis in patients with neuroblastoma." (PMID 30116755, 2018). "In contrast, LIN28B has been shown to be overexpressed in high-risk neuroblastoma, leading to increased MYCN expression and stabilization by both inhibiting the miRNA let-7, and increasing RAN and AURKA expression." (PMID 30200332, 2018). "The F1174L mutation bears strong oncogenic capacity and correlates with MYCN amplification, potentiating the oncogenic activity of MYCN in neuroblastoma, and is linked to acquired resistance to crizotinib." (PMID 29515255, 2018). "Amongst high-risk tumours, which comprise about half of all neuroblastomas, approximately 40% are dependent on MYCN gene amplification (MNA)." (PMID 28602975, 2017). "About 20% of neuroblastomas feature an amplification of the MYCN gene, which is associated with poor prognosis demanding aggressive chemotherapy." (PMID 28862657, 2017). "As MYCN amplification is associated with NB aggressiveness and poor prognosis (MYCN protein expression as a predictor of neuroblastoma prognosis), we evaluated the relation in between MYCN amplification and NEO1/NTN4 expression." (PMID 28038459, 2017). "Constitutively, activated ALK synergizes with MYCN overexpression in inducing neuroblastoma in animal models, and the co-occurrence of ALK F1174 mutations and MYCN amplification defines a subset of neuroblastoma patients with particularly poor outcome." (PMID 28425916, 2017). "MYCN shares the burden of being the cause of neuroblastoma by preventing differentiation and maintaining pluripotency at the expense of cells future." (PMID 29018329, 2017). "A recent analysis on structural variants using whole genome sequencing revealed that TERT promoter rearrangements characterize a subgroup of high-risk neuroblastoma with poor prognosis comparable to MYCN amplified tumors." (PMID 28521285, 2017). "Tumor-associated macrophages (TAMs) are strongly associated with poor survival in neuroblastomas that lack MYCN amplification." (PMID 29207662, 2017). "Neuroblastoma is a tumor of the peripheral sympathetic nervous system for which only a few driver alterations have been described including MYCN amplification and ALK mutations." (PMID 28423360, 2017). "This suggests that the MYCN amplification in neuroblastoma is linked with the up- or down regulation of many genes." (PMID 29137381, 2017). "Children afflicted with neuroblastoma are risk-stratified based upon age at diagnosis, stage of tumor progression, and biologic features including the presence of MYCN-amplification." (PMID 29207623, 2017). "More recently, the role of nf1 mutations, which are associated with a poor outcome in human neuroblastoma, was also analyzed in the zebrafish MYCN model." (PMID 28894696, 2017).
neuroblastoma (continued). "These “high-risk” neuroblastoma are characterized by genomic instability resulting in segmental chromosomal alterations and high-level amplification of the MYCN gene locus." (PMID 28924153, 2017). "Analysis of the high-risk neuroblastoma genetic landscape using a combination of next-generation sequencing approaches resulted in the identification of a recurrent mutation in the MYCN gene (1.7% of cases, resulting in the P44L missense mutation)." (PMID 28587062, 2017). "Neuroblastoma patients with stage 4 disease, those in the high-risk group, and those with non -MYCN-amplified tumors benefited the most from the multidisciplinary team approach." (PMID 27966455, 2017). "The pathologic activation of MYCN plays a central role in high-risk neuroblastoma, with MYCN amplification identified in 25% of primary neuroblastoma tumors and nearly half of high-risk cases." (PMID 28881723, 2017). "Co-targeting of the retinoic acid and TGF-β pathways, through RA and kartogenin (KGN; a TGF-β signalling activating small molecule) combination treatment, induced the loss of viability of MYCN-amplified retinoid-resistant neuroblastoma cells." (PMID 28187790, 2017). "While 20% of neuroblastomas harbor MYCN amplifications, directly classifying them as high-risk, around 50% of high-risk tumors lack MYCN amplification and display molecular diversity within the high-risk tumor group." (PMID 28036269, 2017). "While high NTRK2 expression combined with amplified MYCN is a marker for high-risk neuroblastoma, NTRK2 pathway activation by BDNF ligand treatment is also known to aid RA-mediated differentiation." (PMID 28187790, 2017). "Patients with high risk neuroblastoma along with MYCN amplification typically show high resistance and poor therapeutic benefits." (PMID 29088756, 2017). "The MYCN amplification arises in 20% of all neuroblastoma cases and in ~50% of the cases associated with poor prognosis and survival." (PMID 29137381, 2017). "In a large series of 3501 newly enrolled patients in the COG Neuroblastoma studies undifferentiated neuroblastoma accounted for 4.5% and frequently associated with poor prognosis biomarkers such as advanced disease or MYCN amplification." (PMID 28818093, 2017). "NDRG1 is repressed in cell lines with MYCN amplification and this down-regulation is known to be associated with MYCN effects in neuroblastomas." (PMID 29018329, 2017). "BARD1β not only presents the characteristics of neuroblastoma oncogenes but also enhances MYCN-stabilized high-risk phenotypes." (PMID 28984200, 2017). "In neuroblastoma, the MYC-related transcription factor MYCN is found to be amplified in ~20% of neuroblastomas, and its amplification is associated with poor prognosis." (PMID 28443280, 2017). "Neuroblastoma patients are stratified into low-, intermediate- and high-risk groups based on stage, age, MYCN status, histology and chromosomal ploidy." (PMID 28358317, 2017). "These genes were selected as they have previously been associated with either neuronal differentiation, MYCN or neuroblastoma, but our analysis reveals their opposing transcriptional regulation by RA and MYCN." (PMID 28187790, 2017). "We verified that MLN8237 and VX680 treatment each resulted in loss of p4E-BP1 and MCL-1 in MYCN-amplified neuroblastoma cells, as did knockdown of Aurora A." (PMID 26859456, 2016). "This analysis uncovered the MCL-1 inhibitor NOXA, encoded by PMAIP1, to be significantly higher in MYCN-amplified neuroblastomas." (PMID 26859456, 2016). "As observed in other tumors suffering from RS, such as recombination-deficient ovarian cancers or MYCN-driven neuroblastomas, ES cells present high levels of CHK1 expression, which helps them deal with the presence of RS." (PMID 27577084, 2016).
neuroblastoma (continued). "Oncogenic mutations in the ALK gene play a role in neuroblastoma pathogenesis and are highly correlated with MYCN amplification." (PMID 26771642, 2016). "The most distinct marker for poor survival in neuroblastoma is MYCN gene amplification which is found in approximately 40 % of high-risk neuroblastomas." (PMID 27036398, 2016). "Association of MYCN amplification and epigenetic silencing of several genes in neuroblastoma had been previously reported, although the underlying mechanisms are still under investigation." (PMID 27242543, 2016). "Patients with high risk neuroblastoma and those with MYCN amplification typically show emergence of treatment resistance." (PMID 26934655, 2016). "Mice in which the ALKF1174L hotspot mutation and MYCN are co-expressed (Th-ALKF1174L/MYCN) develop neuroblastoma resistant to treatment with crizotinib." (PMID 27483357, 2016). "While MYCN has been established as a key driver of malignancy in neuroblastoma, the underlying molecular mechanisms are poorly understood." (PMID 27448979, 2016). "We have previously shown that transgenic mice co-expressing an active ALKF1174L mutation with MYCN via the tyrosine hydroxylase promoter potentiates neuroblastoma development characterized by earlier onset, higher penetrance and enhanced lethality." (PMID 27483357, 2016). "In contrast to crizotinib, single agent administration of PF-06463922 caused dramatic tumor inhibition in both subcutaneous and orthotopic xenografts as well as a mouse model of high-risk neuroblastoma driven by Th-ALKF1174L/MYCN." (PMID 27483357, 2016). "Our zebrafish model of MYCN-driven neuroblastoma with nf1 loss is ideally suited for the rapid in vivo analysis of the effects of candidate small-molecule inhibitors selected for this purpose." (PMID 27130733, 2016). "High-risk (HR) neuroblastoma is characterized by metastatic disease and/or amplification of the MYCN proto-oncogene that is a biomarker still used today to stratify risk." (PMID 27683112, 2016). "MYCN, an oncogene and transcription factor, amplified in neuroblastoma cells is associated with neuroblastoma growth and progression possibly by initiating both metabolic privilege mediated by WE and a high proliferative rate." (PMID 27821095, 2016). "About 40 % of high-risk neuroblastoma contain gene amplification of the transcription factor MYCN often leading to high Mycn expression whereas about 6 % of neuroblastomas contain mutation of ALK, the majority seen in connection to MYCN gene amplification." (PMID 27036398, 2016). "Aberrant expression of MYCN is strongly associated with poor outcome, making this oncoprotein one of few proposed targets in molecular therapy for neuroblastoma." (PMID 28713571, 2016). "Having shown that both inhibition and activation of Wnt/β-catenin signalling preferentially reduced cell viability of high MYCN expressing neuroblastoma cells, we next explored how oncogenic MYCN and Wnt are functionally linked." (PMID 27531891, 2016). "Developing a greater understanding of some of the underlying mechanisms of MYCN-mediated neuroblastoma progression is important for identifying genes responsible for tumor progression as well as potential molecular therapeutic targets." (PMID 27448979, 2016). "ABT-199/MLN8237 combination therapy is differentially effective in the high-risk, MYCN-amplified subset of neuroblastoma." (PMID 26859456, 2016). "Here we perform ChIP-sequencing and small RNA-sequencing of neuroblastoma cells to determine the MYCN-binding sites and MYCN-associated microRNAs, and integrate various types of genomic data to construct MYCN regulatory networks." (PMID 27167114, 2016). "In this study, we use a zebrafish model to demonstrate that NF1 loss can potentiate the tumorigenic effects of MYCN-overexpression in high-risk neuroblastoma." (PMID 27130733, 2016).
neuroblastoma (continued). "Prior to high-throughput genomic sequencing, amplification of the oncogenic transcription factor MYCN was identified in 20% of neuroblastoma cases and associated significantly with high-risk disease and poor outcome." (PMID 28035989, 2016). "Here, we have demonstrated that Aurora A inhibition not only leads to mitotic arrest but also leads to loss of p4E-BP1 in MYCN-amplified neuroblastoma cells (resulting in downregulation of MCL-1 as a result of cap-dependent translation inhibition)." (PMID 26859456, 2016). "The deregulation of certain oncogenes such as MYCN in neuroblastoma and C-MYC in lymphoma appears to be associated with an increase in single-agent CHK1 sensitivity, possibly through enhanced replication stress." (PMID 26295308, 2016). "For instance, caspase 8 is often silenced in neuroblastoma, and in TH-MYCN mice, which express MYCN in neural crest cells that form neuroblastomas; caspase 8 deficiencies cause formation of metastatic neuroblastomas in the bone marrow." (PMID 26859456, 2016). "MYCN is broadly considered un-druggable, and amplification of this oncogene is associated with drug resistant fatal high-risk neuroblastoma." (PMID 27531891, 2016). "High-level amplifications of the MYCN oncogene is observed in about 20% of cases, and has long been associated with high-risk disease and poor outcome in neuroblastoma." (PMID 26859456, 2016). "Over the 20-week course of this experiment, neuroblastoma developed in one of the 14 transgenic MYCN-positive zebrafish with wild-type nf1 alleles, consistent with the relatively low penetrance and late onset of these tumors in the wild-type background." (PMID 27130733, 2016). "Poor prognosis and frequent relapses are major challenges for patients with high-risk neuroblastoma (NB), especially when tumors show MYCN amplification." (PMID 26657295, 2016). "Although MYCN has been demonstrated to regulate neuroblastoma cell differentiation, the mechanisms underlying such function are not clearly defined." (PMID 27764804, 2016). "Amplification of the MYCN gene, which occurs in 40-50% of the high risk neuroblastoma cases, remains the major key predictor of poor outcomes." (PMID 26934655, 2016). "These valuable resources allow us to improve our understanding of MYCN regulation in neuroblastoma and help to develop diagnostic tools and effective therapeutic strategies for this cancer." (PMID 27167114, 2016). "Amplification of MYCN is the signature genetic aberration of 20–25% of neuroblastoma and a stratifying marker associated with aggressive tumor behavior." (PMID 26910568, 2016). "While MYCN amplification is the most common genetic event associated with high-risk neuroblastoma, over half of high-risk patients don’t harbor this alteration." (PMID 28035989, 2016). "MYCN amplification occurs in 25 % of all primary neuroblastomas and is used for neuroblastoma risk stratification." (PMID 27515310, 2016). "We also identified a significant association of hASH1 with neuroblastoma stage and MYCN amplification status, pointing to its functional importance in neuroblastoma." (PMID 28066180, 2016). "Many of the high-risk neuroblastoma cells are MYCN-amplified; therefore novel therapeutic strategies directed toward this target are continually being studied." (PMID 27382528, 2016). "MYCN gene amplification occurs in a quarter of primary neuroblastomas and is associated with N-Myc protein over-expression and poor patient survival." (PMID 27764794, 2016). "The developmental context in which neuroblastoma arises appears to be particularly important, with many genes associated with aggressive disease (MYCN, ALK) driving cell proliferation and neuritogenesis." (PMID 28035989, 2016). "Loss of Nf1 has been shown to increase the penetrance of MYCN-induced neuroblastoma in MYCN transgenic mice, and for our studies in zebrafish we determined the extent to which loss of nf1 synergizes with overexpression of the MYCN oncogene in this disease." (PMID 27130733, 2016).